MMP9 (matrix metallopeptidase 9)
Diseases named in the same sentence as MMP9 in open-access papers (continued):
Sharing a sentence is not in itself a finding about the gene and the disease.
breast carcinoma (continued). "Furthermore, the elimination of TAMs by TAMpepK inhibited the metastasis of breast cancer as well as primary tumor growth and metastatic genes, including HIF-1, Ym1, and MMP9." (PMID 35216272, 2022). "Decreased expression and proteolytic activity of MMP-9 and MMP-2 were observed in breast tumors after NC-based treatment, suggesting that treatment with NC at a low concentration inhibits breast cancer cell metastasis by suppressing the Src/FAK signaling pathway." (PMID 36362132, 2022). "High levels of blood MMP-9 and TIMP-1 indicate worse prognoses in lung cancer and breast cancer." (PMID 35629249, 2022). "Resveratrol showed a dose-dependent inhibition of TGF-β1-induced EMT-induced cell migration in the human MDA231 breast cancer cell line, decreased the expression levels of MMP-2 and MMP-9, and effectively inhibited MDA231 human breast cancer lung metastasis of cancer." (PMID 36686745, 2022). "Thus, this study found that orosmucoid 1 upregulation in breast cancer cells increased MMP-2 and MMP-9 expression, activated Akt/ERK signaling pathways, all of which stimulating epirubicin resistance via apoptosis inhibition." (PMID 35586209, 2022). "In breast cancer, cytoplasmic polyadenylation element-binding protein 1 (CPEB1) mediates EMT and metastasis by enhancing the shortening of the polyA tail of MMP9, which lowers MMP9 translation." (PMID 36076302, 2022). "Formononetin as anti-invasive agent for breast cancer, could inhibits migration and invasion of breast cancer cells by suppressing MMP-2 and MMP-9 through PI3K/AKT signaling pathways." (PMID 35922850, 2022). "MMP9 levels were significantly higher in the breast cancer group, regardless of BC subtype, compared to the benign tumour group (n = 10)." (PMID 35818030, 2022). "Eugenol at an IC50 value of 1.5 μg/mL is a potent cytotoxic agent which suppressed metastasis and cancer cell migration by downregulating 34.3% matrix metalloproteinase (MMP-9) and 13.7% paxillin mRNA expression levels, respectively, in MCF-7 breast cancer cells." (PMID 36362950, 2022). "In reference to MMP-9 and TIMP-1, a significant correlation has been previously reported between serum expression and breast disease severity score, suggesting the potential application of its measurement in monitoring breast cancer progression." (PMID 35222743, 2022). "In contrast, in MDA-MB-231 breast cancer cells, it was demonstrated that PIMT was stimulated by a co-treatment with TGF-β1/TNF-α, which also increased mRNA levels of EMT markers including those of Snail, Slug, MMP-2, MMP-9, and Fibronectin." (PMID 35628507, 2022). "In mouse models of breast cancer bone metastases established by injection of human MDA-MB-231 breast cancer cells, expression of osteolytic factors (RANKL, Cathepsin-K, and MMP9) was higher in ovariectomized (OVX) mice mimicking the postmenopausal bone microenvironment, compared with sham operation." (PMID 36419084, 2022). "Moreover, it was found that migration and invasion of breast cancer cells induced by BMP also correlate with increased expression of metalloproteinases, namely MMP-2, MMP-9 and MMP-14." (PMID 36139691, 2022). "As for MMP-9, several studies have demonstrated that its positive or high expression in tumor cells or stromal cells is a negative prognostic factor for breast cancer." (PMID 36741729, 2022). "One of them is silibinin A, a compound isolated from milk thistle seeds, which binds the active site of MMP9 and inhibits TPA (12-O-tetradecanoylphorbol-13-acetate)-induced MMP9 and COX-2 expression via inhibition of the Raf/MEK/ERK pathway in breast cancer cells." (PMID 35406619, 2022). "In 4T1 murine breast cancer cells, HSP could induce apoptosis and stop metastasis through down-regulating MMP-9 expression and arresting cell cycle at Sub G1 phase when administered at 50–100 μM concentration." (PMID 35128104, 2022).
breast carcinoma (continued). "The qPCR analysis demonstrated that the synthesized nanoparticles desirably affected the gene expression in the studied breast cancer cell lines; resulting in down-regulation of the MMP-2, MMP-9, cyclin D, and cyclin E while up-regulation of caspase-3 and caspase-9." (PMID 35875198, 2022). "In our study, it was discovered that BHLHE41 overexpression largely enhanced the levels of BHLHE41 and E-cadherin but repressed the levels of HIF-1α, N-cadherin, vimentin, and MMP9 in hypoxia-induced CC cells, which was consistent with the report of BHLHE41 in breast cancer." (PMID 35615737, 2022). "Zymomonas' levan is involved in MMP-9 activation and extracellular matrix remodeling and inflammation and also to induce changes in oxidative states leading to antiproliferative and proapoptotic effects in MCF7 breast cancer cells." (PMID 33659025, 2021). "The osteotropic behavior of tumor cells is driven by bone-specific metastatic signaling molecules such as matrix metalloproteinase-9 (MMP-9) and bone morphogenetic protein-7 (BMP-7), which are highly expressed in prostate and breast cancers and promote EMT and bone invasion." (PMID 34440874, 2021). "Importantly, MMP-9 overexpression was found to be an important endpoint for the more aggressive subtypes, triple-negative and HER2-positive breast cancers." (PMID 34055644, 2021). "Finally, we conducted Western Blot, and the results suggested that in MDA-MB-231 cells, C5AR2 overexpression led to the obviously upregulated levels of MMP2 and MMP9, indicating that C5AR2 was related to EMT in breast cancer." (PMID 34595119, 2021). "Accordingly, in murine breast cancers, monocyte/macrophages are major MMP-9 producers and have a strong impact on cancer cell extravasation since MMP-9 expression and cancer extravasation are strongly reduced in tumor mice ablated of CCR2+ inflammatory monocytes." (PMID 33783686, 2021). "Thus, a higher dose of calycosin led to a reduction of migration and invasion of human breast cancer cells, by targeting Foxp3-mediated VEGF and MMP-9 expression." (PMID 34462889, 2021). "TAK-242, a specific inhibitor of TLR4, was reported to considerably attenuate epithelial–mesenchymal transition (EMT) in ovarian and breast cancer cells by suppressing extracellular degradation through targeting TLR4 and regulating matrix metalloproteinase-2 (MMP-2) and MMP-9 expression." (PMID 33576897, 2021). "Furthermore, piceatannol inhibits the invasion of breast cancer cells through the PI3K/AKT and NF-κB pathways and inhibition of MMP-9." (PMID 34884588, 2021). "Rebeca Santaolalla in a study on the breast cancer cells also showed that TLR-4 enhances migration of breast cancer cells, via PI3K/AKT/GSK3β, and promotes transcription of downstream-catenin target genes (MMP7, MMP9, and VEGFA), leading to breast cancer metastasis." (PMID 34904014, 2021). "Moreover, MMP-9 was also eminently expressed in TNBC and HER2-enriched breast cancer cells when compared with that in other subtypes." (PMID 34181339, 2021). "CXCL13 facilitates breast cancer cell line migratory activity via the nuclear factor kappa-B ligand (RANKL)-Src pathway, which mediates the upregulation of EMT regulators and matrix metalloproteinase-9 (MMP9)." (PMID 34947813, 2021). "Therefore, in this study, we also detected the effect of MTDH on Gem-treated breast cancer cells and the expressions of MMP-2 and MMP-9 proteins." (PMID 34552061, 2021). "In addition, kaempferol can reduce both the activity and expression of MMP-2, MMP-9, and cathepsin in MCF-7 breast cancer cell lines." (PMID 34572548, 2021).
breast carcinoma (continued). "In MCF-7 breast cancer cells treated with 12-O-tetradecanoylphorbol-13-acetate (TPA), luteolin suppressed the expression of interleukin 8 (IL-8) and the activation of matrix metalloproteinase 9 (MMP-9), which play important roles in breast cancer proliferation." (PMID 34513708, 2021). "Further bone-derived soluble factors cooperate with tumor-derived laminin 511, an adhesive and pro-migratory substrate for tumor cells, to facilitate migration and invasion of bone-metastatic breast cancer cells via an upregulation of the AKT signaling and MMP9." (PMID 34064589, 2021). "Five proteins (LMAN1, AZI2, STAU2, MMP9 and PLOD1) from a systemic analysis of a variety of array data of breast cancer patients were subjected to immunofluorescence staining to evaluate the presence of fixed WBCs on 96-well plates from 363 healthy females and 358 female breast cancer patients." (PMID 33441653, 2021). "MMP-9 plays a role in angiogenesis, growth, and metastasis in breast cancer, consequently resulting in breast cancer progression, with MMP-9 being a potential negative prognostic marker." (PMID 34944905, 2021). "In the MCF-7 breast cancer cell line, Kae inhibits the protein expression of epithelial-mesenchymal transition-related markers and suppresses metastasis-related markers such as MMP-2 and MMP-9." (PMID 33498927, 2021). "Similar to MMP9, MMP2 also increases the invasion of breast cancer cells." (PMID 33832499, 2021). "DACH1 could decrease the expression of MMP9 and MMP2 in in gastric cancer, so the effect of DACH1 on the expression of MMP9 and MMP2 was examined in breast cancer cells." (PMID 34772908, 2021). "This retrospective cohort study shows the immunohistochemical expression levels of MMP-1, MMP-2, MMP-3, and MMP-9 in 154 women with breast cancer and 42 women without tumor disease." (PMID 34445715, 2021). "Among these proteins, MMP-2 and MMP-9 showed the highest correlation with SCUBE3, suggesting that they may be functional partners in breast cancer." (PMID 34006286, 2021). "This interesting role in breast cancer may be due to the inhibition of TGF-β with subsequent activation of programmed cell death 4 (PDCD4), decrease of MMP-3 and MMP-9 and increase of cell adhesion." (PMID 34884877, 2021). "Based on previous pharmacological studies of SLB and CT anti-metastasis, and the roles of specific indicators in inducing breast cancer metastasis in tumor microenvironments, CD31, MMP-9, and TGF-β1 expression were detected in breast cancer and lung metastasis tissue." (PMID 32473632, 2020). "Mechanistically, we showed that both knockdown of PTTG1 expression and simvastatin treatment potently attenuated breast cancer cell invasion, presumably through inhibition of the expression of PTTG1 downstream target genes, such as MMP-2, MMP9, c-myc, FGF-2, and cyclin D3." (PMID 33250768, 2020). "For example, in breast cancer, upregulation of CXCR7 regulates metastasis by enhancing the expression of the adhesion molecule vascular cell-adhesion molecule (VCAM)-1 and MMPs such as MMP-2 and MMP-9." (PMID 32575507, 2020). "These dysregulations were associated with lymph node metastases and lower overall survival rates, suggesting that the levels of MMP-9 and TIMP-1 could be further evaluated to predict prognosis and progression of breast cancer." (PMID 32392801, 2020). "These authors showed that PPARγ ligands reduced the invasive capabilities of MDA-MB-231 breast cancer cells, enhancing the ratio of metallopeptidase inhibitor 1 (TIMP-1), the tissue inhibitor of MMPs, to MMP-9 with a consequent reduction of the activity of this enzyme." (PMID 33352766, 2020).
breast carcinoma (continued). "Indeed, when comparing the human breast cancer cell line MDA-MB435 (ICAM-1+ and MMP-9−) to transfected MDA-MB435 (ICAM-1+ and MMP-9+), the transfected cells had a higher concentration of soluble ICAM-1 in the supernatant and were more resistant to NK cells." (PMID 32063906, 2020). "For instance, CD147 could promote breast cancer cell metastasis and invasion by contribution of MMP2, MMP9, and VEGF expression, and CD147-mediated chemotaxis of CD4+CD161+ T cells may contribute to local inflammation in rheumatoid arthritis." (PMID 33015178, 2020). "Additionally, HCT and PR extracts also decreased the migration and invasion of both breast cancer cell lines through inhibition of MMP-2 and MMP-9 secretion." (PMID 32155880, 2020). "Curcumol could inhibit MMP-9 via the c-Jun N-terminal kinase (JNK) 1/2 and NF-κB signaling pathways in breast cancer cells." (PMID 32210799, 2020). "In this study, we reported that arctigenin, a bioactive compound from Arctium lappa L., could decrease tumor-promoting cytokines GM-CSF, MMP-3, MMP-9 and TSLP in breast cancer cells." (PMID 32887217, 2020). "In breast cancer, COL4A1 induced MMP-9 expression by activating Src phosphorylation." (PMID 32746865, 2020). "MCF-7 breast cancer cells, which can be used as a model system for regulated exocytosis of MMP-9, were used to probe the lipid environment of secretory vesicles containing MMP-9 and their subsequent exocytosis in living cells." (PMID 32829709, 2020). "In this study, we showed that CME could induce intrinsic and extrinsic pathways of apoptotic cell death, and suppress MMP-9 and metastasis in the MDA-MB-231 TNBC breast cancer cell line." (PMID 32328465, 2020). "And Snail can also inhibit the expression of other epithelial genes such as Claudin1 and Muc1 and promote the expression of other mesenchymal genes such as fibronectin, MMP9 and vimentin, which activates EMT and is related to tumor metastasis, recurrence and poor prognosis in breast cancer." (PMID 32028981, 2020). "Recently, it has been reported that C-reactive protein (CRP) induced upregulation of ITGA2 and matrix metalloproteinase-9 (MMP-9) expressions by activating focal adhesion kinase, pilin, and ERK signal pathway, thus promoting the invasion of breast cancer cells." (PMID 32904605, 2020). "In addition, ARG inhibited the metastasis of human breast cancer cells by reducing the activity of MMP2, MMP9, and heparanase protein." (PMID 33015162, 2020). "MMP9 was critical in TGFβ-induced invasion and depletion of SENP5 resulted in a dramatic reduction of MMP9, which indicates that SENP5 regulated the invasion of breast cancer by TGFβ-induced MMP9." (PMID 33273928, 2020). "In addition, association between gallic acid and ECGC attenuated MDR in doxorubicin-resistant breast cancer cells through a concentration-dependent inhibition of metalloproteinases (MMP-2 and MMP-9)." (PMID 31936346, 2020). "We reported that skeletal muscle of mammary tumor-bearing mice compared to wild type mice had elevated ECM deposition, which could be due to a reduction of Mmp-9." (PMID 31941005, 2020). "Another study on breast cancer showed an association between MMP8 levels and the levels of metalloproteinase inhibitor 1 (TIMP-1) and MMP9 but not with tissue plasminogen activator, urokinase or their inhibitor (PAI-1)." (PMID 31514474, 2019). "Fourth, In addition to MMP9, in the breast cancer cells, BMAL1 also up-regulated the expression of TNF-a, IL8, and uPA at the mRNA level, which are all target genes of NF-κB, suggesting a potential role of BMAL1 in NF-κB/MMP9 pathway." (PMID 31346317, 2019). "Matrix metalloproteinase (MMP) family such as MMP2 and MMP9, the vital epithelial-mesenchymal transition (EMT)-related factor vimentin, and the actin-bundling protein fascin play essential roles in breast cancer metastasis." (PMID 31186039, 2019).
breast carcinoma (continued). "Hence, the knockdown of MMP-9 leads to down-regulation of EMT that inhibites the migration and invasion of aggressive breast cancer cells." (PMID 30728391, 2019). "The negative effect of miR-140 on MMP9 has been reported to inhibit breast cancer invasion, while estrogen has been shown to suppress MMP13 expression through the upregulation of miR-140 in the development of menopausal arthritis." (PMID 31915516, 2019). "PNS significantly inhibits the metastasis of breast cancer cells, and its function is to upregulate the expression of E-cadherin and cancer suppressor genes Brms1, Mtss1, and Timp2 and downregulate the expression of MMP3, MMP-9, and vimentin." (PMID 31636686, 2019). "Compared with healthy volunteers, the extremely high serum levels of MMP-9 and CCL21 in patients with colon cancer, of CCL11 in patients with gastric cancer, of CCL2/MCP-1 in patients with breast cancer and of CXCL13 in patients with liver cancer have been reported." (PMID 31754081, 2019). "Furthermore, quercetin also induced Akt-mTOR mediated autophagy in breast cancer cells where it reduced the migration and metastasis of cells through MMP-2, MMP-9, and VEGF inhibition." (PMID 31064104, 2019). "In addition, SDF-1α binds to CXCR7, another chemokine receptor that is highly expressed on breast cancer cells, and enhances CXCR7-mediated tumor migration and metastasis by activating STAT3, MMP9, MMP2 and VCAM-1." (PMID 31219799, 2019). "Our results showed that ENO1, MMP-2 and MMP-9 are overexpressed in breast cancer tissues compared to the non-tumoral adjacent one, and how their higher expression level is associated with a worse prognosis." (PMID 31416219, 2019). "Additionally, ginsenoside CK also has a good effect in inhibiting breast cancer invasion and metastasis and its mechanism is related to the downregulation of MMP-2 and MMP-9 expression." (PMID 31636686, 2019). "Finally, Knock down of STAT3 in the multidrug resistant breast cancer, SK-BR-3/EPR, cell line inhibited cell invasion and downregulated MMP-9 in these cells." (PMID 31456939, 2019). "Furthermore, priming of animals with breast cancer-derived exosomes containing high annexin A2, led to an increased level of VEGFR1 in lung and brain sections, with a concordant increase in MMP9 in tissues." (PMID 31555295, 2019). "The interaction between macrophages and breast cancer cells has been reported to increase levels of various tumor promoting factors such as COX-2, and MMP-9 which, in turn, supports the breast malignancy and an increase of TAM density in the tumor microenvironment." (PMID 31126309, 2019). "MMPs, especially MMP9 and MMP2, are crucial biomarkers for migration and invasion in breast cancer." (PMID 31488193, 2019). "Our present study also examined the regulatory effects of CCL2 on different breast cancer cells, while disrupting CCL2-CCR2 axis by CCR2 antagonist RS102895 could attenuate these effects partially due to downregulation of MMP-9 and VEGF expression in vitro." (PMID 29934505, 2018). "Our results demonstrated that MMP-9 activities in MDA-MB-231 cells were reduced after actein treatment, suggesting that actein could inhibit breast cancer cell migration via reducing the degradation of ECM and hence cancer cell invasion." (PMID 30618758, 2018). "In vitro and in vivo studies on the effect of MAG against cells of the highly invasive human breast cancer cell line MDA-MB-231 and female nude immunodeficient mice revealed that MAG downregulates MMP-9 expression by inhibiting the binding of NF-κB to the MMP-9 promoter." (PMID 30103472, 2018). "Thus, to study the mechanisms of the inhibitive effect of nobiletin on migration of breast cancer cells, we measured the expression of MMP-2 and MMP-9." (PMID 30574046, 2018).